RELA (RELA proto-oncogene, NF-kB subunit)
Diseases named in the same sentence as RELA in open-access papers (continued):
Sharing a sentence is not in itself a finding about the gene and the disease.
glioblastoma (22 papers, 2013 to 2025). The most malignant astrocytic tumor (WHO grade IV). "Nonetheless, it may be of interest that TERT mRNA expression was elevated in RELA fusion-positive ST-EPNs, to an extent which far exceeded that in glioblastomas with TERT promoter mutations." (PMID 30514397, 2018). "mRNA and protein expression of NF-κB p65 (RelA) and TNFα were significantly increased in glioblastoma biopsy samples." (PMID 37892820, 2023). "Compared to the stress group, celecoxib significantly reduced the expression of NF-κB p65 (RelA) and TNFα in the glioblastoma SF-767 cell line in a dose-dependent manner." (PMID 37892820, 2023). "Results: demonstrated the upregulation of NF-κB p65 (RelA) and TNFα and celecoxib reduced the viability of the human glioblastoma cell line SF-767, cell proliferation, and NF-κB p65 (RelA) and TNFα expression in a dose-dependent manner." (PMID 37892820, 2023). "In vitro expression study of NF-κB p65 (RelA) and TNFα in the SF-767 glioblastoma cell line after treatment with temozolomide and celecoxib." (PMID 37892820, 2023). "The lncRNA MATN1-AS1 has been shown to inhibit proliferation in the context of glioblastoma due to its ability to inhibit expression of RELA." (PMID 35202088, 2022). "The plasmid was co-transfected with the RelA overexpression plasmid alone or in combination with sh-HIF1α in U87 and U251 glioblastoma cells." (PMID 26172294, 2015). "PDK4 was shown to be abundant in patient glioblastoma compared to normal tissue, and indirectly reducing its expression through shRNA targeting the RelA subunit of NF-kB resulted in reduced growth of xenografts in nude mice." (PMID 26576332, 2015). "MATN1-AS1 inhibits the proliferation and invasion of glioblastoma cells through RELA regulation." (PMID 35154340, 2021). "LncRNA MATN1-AS1 prevents glioblastoma cell from proliferation and invasion via RELA regulation and MAPK signaling pathway, suggesting that LncRNAs could be used as diagnostic biomarkers and potential therapeutic targets in GBM in the future." (PMID 33505307, 2020). "In glioblastoma cells, the interaction of PPARα and RelA only appeared in the cytoplasm." (PMID 26172294, 2015). "Following this, to determine whether NF-κB/RelA is responsible for FF-mediated anti-glycolysis in glioblastoma cells, we performed glycolysis stress test assays." (PMID 26172294, 2015). "By utilizing patient-derived glioblastoma stem cells and CRISPR gene editing of the RELA gene, we demonstrate a crucial role for RelA lysine 310 acetylation in recruiting BET proteins to chromatin for MES gene expression and GBM cell invasion upon PTEN loss." (PMID 37461511, 2023). "Here, using patientderived glioblastoma stem cells (GSCs) and CRISPR gene editing of the RELA gene, we show that RelA is crucial for ECM gene expression and GBM cell invasion associated with MES transition in the context of PTEN loss." (PMID 37461511, 2023). "We checked the effect of NF-κB/RelA on the expression of PKM1, PKM2, hnRNPΙ, hnRNPA1, and hnRNPA2 in U87 and U251 glioblastoma cells." (PMID 26172294, 2015). "For instance, increased NF-κB activation and nuclei translocation of p65/RelA has been reported in glioblastoma, leukemia, and ovarian CSCs compared to the non-CSCs." (PMID 37370720, 2023). "Compared to the stress group, the TMZ did not significantly reduce the expression of NF-κB p65 (RelA) and TNFα in the glioblastoma SF-767 cell line in a dose-dependent manner." (PMID 37892820, 2023). "Furthermore, NF-κB/RelA obviously promoted glioblastoma cell glycolysis depending on PKM2 but not PKM1 (data not shown)." (PMID 26172294, 2015).
melanoma (22 papers, 2011 to 2024). A malignant, usually aggressive tumor composed of atypical, neoplastic melanocytes. "Analysis of four independent melanoma clinical cohorts showed that RelA overexpression is associated with worse overall survival, supporting its tumor-promoting role in this system." (PMID 27203220, 2016). "Thus, loss of miR-7-5p in melanoma promotes RelA overexpression, facilitating melanoma growth and metastasis and ultimately resulting in a worse clinical outcome." (PMID 27203220, 2016). "Finally, analysis of gene array datasets from multiple melanoma patient cohorts revealed an association between elevated RelA expression and poor survival, further emphasizing the clinical significance of RelA and its downstream signaling effectors." (PMID 27203220, 2016). "Importantly, high RelA expression is associated with a worse clinical outcome in melanoma patients." (PMID 27203220, 2016). "This is in addition to its recently investigated role promoting local invasion by increased expression of matrix metalloprotease (MMP)‐3 via p65/RelA in melanoma cells." (PMID 38775220, 2024). "B16 melanoma cells showed a reduction in RelA phosphorylation and, thus, in NFκB activity after STAT3 knockdown." (PMID 38571491, 2024). "When melanoma cells were treated with IL-1β (100 pM) for 0–180 min, p65/RelA and p105 phosphorylation was observed at 5–15 min and 5–30 min after stimulation, respectively." (PMID 36445856, 2022). "Then we evaluated the effect of IL-1β on MMP-3 mRNA expression in p65/RelA- or p105-depleted melanoma cells." (PMID 36445856, 2022). "In human melanoma cell lines, the decreased levels of survivin (by both SLs) and the p65/RelA subunit of NF-κB (only by inuviscolide) suggest an apoptotic induction." (PMID 36359261, 2022). "The analysis of melanoma patient samples revealed a correlation between RelA expression and poor survival." (PMID 33806891, 2021). "DGKα activates NF-κB through PKCζ-dependent phosphorylation at Ser-311 of the p65/RelA subunit of NF-κB in AKI melanoma cells." (PMID 34680338, 2021). "Collectively, these data indicated that NVD-BM promoted tumor regression by decreasing phosphorylated Akt1 levels, and inhibiting free RELA translocation into the nucleus in melanoma cells." (PMID 32712598, 2020). "Further, it has been demonstrated that miR-7-5p, another tumor suppressor miRNA that is frequently downregulated in melanoma, inhibits melanoma cell proliferation, and metastasis by directly suppressing RelA/NF-κB." (PMID 29701682, 2018). "To exclude technical problems in our experiments, we also used a human melanoma cell line A375 as a control to determine the localization patterns of RelA, RelB, and CUL4B." (PMID 29377600, 2018). "Taken together, our data show that miR-7-5p is a potent inhibitor of melanoma growth and metastasis, in part through its inactivation of RelA/NF-κB signaling." (PMID 27203220, 2016). "Of these, we confirmed nuclear factor kappa B (NF-κB) subunit RelA, as a novel direct target of miR-7-5p in melanoma cells, such that miR-7-5p suppresses NF-κB activity to decrease expression of canonical NF-κB target genes, including IL-1β, IL-6 and IL-8." (PMID 27203220, 2016). "Collectively, these data suggest that miR-7-5p is a potent inhibitor of melanoma growth, migration and invasion, at least in part through the targeted reduction of RelA expression/activity and its downstream targets." (PMID 27203220, 2016). "We elected to focus on the NF-κB subunit RelA (p65) for further functional studies, given its prognostic significance in melanoma and its inverse correlation with miR-7-5p levels." (PMID 27203220, 2016). "Taken together, these data suggest that RelA overexpression and low miR-7-1 levels are indicators of a poor prognosis in melanoma." (PMID 27203220, 2016).
melanoma (continued). "Comparisons across these four datasets showed high expression of either RelA (consensus HR = 1.47), POLE4 (consensus HR = 1.39) or SP1 (consensus HR = 1.48) was consistently associated with an increased risk of death in melanoma." (PMID 27203220, 2016). "In melanoma, gene transfer approaches have been used to inhibit the NF-κB pathway by inactivating RelA or by overexpressing IκB." (PMID 22095230, 2011). "To confirm the contribution of NF-κB to MMP-3 mRNA expression mediated by IL-1β, we investigated whether IL-1β induced the mRNA expression of MMP-3 in p65/RelA or p105 knockdown melanoma cells." (PMID 36445856, 2022). "Interestingly, we observed the significant attenuation in MMP-3 mRNA expression in p65/RelA-depleted melanoma cells compared to p105 siRNA or the control scramble siRNA-transfected cells." (PMID 36445856, 2022). "In melanoma cells, a study has highlighted that some components of the NF-kB pathway family, such as p50 and p65 (RelA) subunits, are overexpressed in the nuclei of dysplastic nevi and melanoma cells compared to those of normal nevi and healthy melanocytes, respectively." (PMID 35806253, 2022). "Therefore, the relationship between p65/RelA and such transcription factors must be determined to elucidate the expression of MMP-3 via activation of NF-κB p65/RelA in canine melanoma cells." (PMID 36445856, 2022). "Thus, it seems possible that miR-7-5p can directly target RelA in melanoma, and that, in turn, NF-κB can act in a reciprocal feedback loop to downregulate expression of miR-7-5p." (PMID 27203220, 2016). "As RelA is a NF-κB subunit responsible for activating the transcription of many genes, we assessed the impact of miR-7-5p on NF-κB transcriptional activity in melanoma cells." (PMID 27203220, 2016). "Thus, RelA knockdown was able to recapitulate the phenotypic effects of ectopic miR-7-5p overexpression in melanoma cells." (PMID 27203220, 2016). "Furthermore, transfection of 1205Lu cells with RelA siRNAs significantly reduced the rate of cell migration and invasion, impaired wound closure in a wound healing assay, and suppressed invasion of melanoma spheroids." (PMID 27203220, 2016). "Further analyses of these data revealed an inverse correlation between miR-7-1 and RelA levels in melanoma and that miR-7-1 levels were associated with survival, consistent with a model in which reduced expression of miR-7-5p promotes RelA overexpression and facilitates melanoma progression." (PMID 27203220, 2016). "Our study shows that RelA is a direct target of miR-7-5p, via two independent binding sites in its 3′-UTR, which reduces its expression, activity and downstream signaling, and our functional experiments validate RelA as a critical mediator of the anti-metastatic effects of miR-7-5p in melanoma." (PMID 27203220, 2016). "Importantly, the effects of miR-7-5p on melanoma cell growth, cell cycle, migration and invasion were recapitulated by RelA knockdown." (PMID 27203220, 2016). "Moreover, direct interaction and dephosphorylation of RelA with PP2A was demonstrated in Sulindac treated melanoma cells." (PMID 26131975, 2015). "In melanoma cells, recent studies have highlighted that some components of NF-κB family, such as p50 and p65/RelA proteins, are overexpressed in the nuclei of dysplastic nevi and melanoma cells compared to those of normal nevi and healthy melanocytes, respectively." (PMID 22433222, 2012). "Importantly, using siRNAs against RelA, we were able to recapitulate the functional effects of miR-7-5p on melanoma cell proliferation, migration and invasion, thus validating RelA as a direct, functional target of miR-7-5p in melanoma." (PMID 27203220, 2016). "B16 mouse melanoma tumor cells and DU145 prostate cancer cells, showed high STAT3 activity by increasing phosphorylation of RelA protein in the presence of TNF-α." (PMID 38571491, 2024).
melanoma (continued). "In the present study, we demonstrate that the canonical NF-κB signaling pathway, NF-κB p65/RelA activation, is involved in the IL-1β mediated-MMP-3 expression in canine melanoma cells." (PMID 36445856, 2022). "Our results showed that RELA and STAT1 activated NVD-BM expression in the presence of doxycycline, and slowed melanoma cell growth and migration." (PMID 32712598, 2020). "The dual-input signals, RELA proto-oncogene (RELA) and signal transducer and activator of transcription 1 (STAT1), activated NVD-BM expression and repressed melanoma cell proliferation and migration." (PMID 32712598, 2020). "Next, we sought to establish a functional role for RelA as a miR-7-5p target in melanoma, such that repression of RelA and its downstream signaling might in part explain the capacity of miR-7-5p to inhibit proliferation, migration and invasion of melanoma cells." (PMID 27203220, 2016). "Together, these data suggest that in melanoma cells, miR-7-5p directly targets two sites within the 3′-UTR of RelA to inhibit RelA mRNA and protein expression." (PMID 27203220, 2016). "Further, aberrant expression of some of these genes including RelA, POLE4 and SP1 had prognostic implications in terms of melanoma patient survival." (PMID 27203220, 2016). "However, we observed that RelA was completely dispensable for CD8+ T-cell priming, accumulation and function in melanoma and colon adenocarcinoma." (PMID 38504985, 2024). "Thus, our genetic circuit effectively sensed the dual-input of RELA and STAT1 signals, and induced NVD-BM actuator expression to rebuild cholesterol metabolism by converting cholesterol to 7-DHC, promoting melanoma cell regression." (PMID 32712598, 2020). "Finally, RELA and STAT1 were selected as dual-input signals for a genetic biosensor in melanoma cells." (PMID 32712598, 2020). "To confirm the direct regulation of RelA expression by miR-7-5p in melanoma, we used quantitative real-time PCR (RT-qPCR) and western blotting and found that miR-7-5p reduces RelA mRNA and protein expression in WM266-4, A2058 and 1205Lu melanoma cells." (PMID 27203220, 2016).
gastric cancer (21 papers, 2011 to 2025). A primary or metastatic malignant neoplasm involving the stomach. "The dysregulation of NF-κB/RELA promotes distant metastasis in gastric cancer, suggesting its potential as a novel therapeutic target." (PMID 35267457, 2022). "Overall, we suggest that LOC441461 modulates gene transcription, inducing the malignancy of gastric cancer by interacting with RELA, IRF1, ESR1, AR, POU5F1, TRIM28, and GATA1." (PMID 35267457, 2022). "In gastric cancer, “genome-wide screenings” were carried out where RelA and FOS proteins were identified as targets of miR-7; repressing the expression of these proteins in turn prevented proliferation and tumorigenesis in gastric cancer cells." (PMID 36012357, 2022). "A significantly higher expression level of NF-κB/RelA and its target genes, c-myc and cyclinD1, was also detected in intestinal-type gastric carcinoma." (PMID 34440074, 2021). "Our results show that depletion of USP47 in AGS gastric cancer cells results in decreased protein levels of phospho-RelA and β-transducin repeat-containing protein (βTrCP)." (PMID 29786670, 2018). "Overexpression of IGFBP-3 resulted in significant inhibition of total and phosphorylated RelA and IκB-proteins in gastric cancer cells and in reduced expression of NF-κB-regulated cell adhesion molecules, ICAM-1 and VCAM-1." (PMID 28350359, 2017). "RelA expression in gastric cancer tissue strongly correlated with abundance of other tumor- and metastasis-promoting markers, including STAT3, MMP-9, IL-6 and VEGF." (PMID 28350359, 2017). "CHIP overexpression in the AGS gastric cancer cells inhibited RelA and RelB via most likely TRAF2 reduction." (PMID 28350359, 2017). "In human stage IV gastric carcinoma, RelA expression was found to decrease, and a group of patients with negative RelA demonstrated significantly increased overall survival after treatment with paclitaxel/LV5Fu2 or FOLFOX." (PMID 28350359, 2017). "In human gastric carcinoma, miR-7 and miR-9, which target RelA, c-Fos and NF-κB1/p50, respectively, and miR-508-3p, which targets both RelA and NF-κB1/p50, were down-regulated." (PMID 28350359, 2017). "Previous work from our group showed that NFκB RelA protein expression is higher in EBV-positive than in EBV-negative stomach cancer, and that BARF1 promotes stomach cancer cell proliferation by upregulating NFκB." (PMID 27438138, 2016). "Hypoxia-inducible factor-1α activation positively correlated with RelA activation in clinical gastric cancer samples (P<0.001)." (PMID 21119667, 2011). "Nuclear expressions of HIF-1α and NF-κB/RelA were assessed in 251 human gastric carcinoma specimens by immunohistochemical tissue array analysis." (PMID 21119667, 2011). "Indeed, Nexrutine has been found to suppress the expression and phosphorylation of RELA in gastric cancer cells, leading to a less malignant phenotype." (PMID 38270298, 2024). "However, in human stage IV gastric carcinoma, RelA expression was found to decrease, which was predictive of a better efficacy of treatment with paclitaxel/LV5Fu2 or FOLFOX." (PMID 34440074, 2021). "The positive correlation of FAT1 and NFкB (RelA) in other tumors like pancreatic, hepatocellular, lung and stomach cancers suggests that the same mechanism may be operative in these tumors also." (PMID 31992226, 2020). "However, further research demonstrated that RelA and NF-κB1/p50 were up-regulated in gastric cancer and cancer cell lines." (PMID 28350359, 2017). "The interaction of the transcription factors RELA, IRF1, ESR1, AR, POU5F1, TRIM28, and GATA1 with LOC441461 affected the degree of the malignancy of gastric cancer by modulating gene transcription." (PMID 35267457, 2022). "Similar to AGS cells, knockdown of USP47 in gastric cancer cell line (NCI-N87) constitutively decreased βTrCP levels, and reduced nuclear translocation of RelA." (PMID 29786670, 2018).
gastric cancer (continued). "Overexpression of ING4 resulted in the down-regulation of RelA, p-IκBα, MMP-9 and uPA proteins and inhibited proliferation and invasion in gastric carcinoma cell lines MKN-28, SGC-7901 and MKN-45." (PMID 28350359, 2017). "Enhancer of zeste homolog 2 (EZH2) activates Ras and p65/RelA (a measure of NF-κB activity), and high EZH2 expression has been correlated with poor prognosis in several tumors, including gastric cancer." (PMID 21951562, 2011). "Changes in the expression of p105/p50, RelA and IKKα, RelA phosphorylation and cellular localization, as well as overexpression of target genes, including IL-6, matrix metalloproteinases, VEGF, were described in gastric cancer tissue." (PMID 33825941, 2021). "However, the expression profile, clinical relevance and dysregulated mechanism of miR-7 and NF-κB RelA/p65 in human gastric cancers (GC) metastasis remain largely unknown." (PMID 30728051, 2019). "Later, a link between high cytoplasmic but not nuclear RelA and a worse survival of gastric cancer patients was described." (PMID 28350359, 2017). "Strong correlation between higher expression levels of RelA, c-Myc, cyclin D1, Bcl-XL in intestinal but not diffuse types of gastric carcinoma was also found." (PMID 28350359, 2017). "A recent study in gastric cancer found miR-7 to be involved in a negative feeback loop with IKKε and v-Rel avian reticuloendotheliosis viral oncogene homolog A (RELA)." (PMID 26308064, 2015). "Indeed, intraperitoneal administrations of RelA siRNA or nafamostat mesilate (FUT-175), a synthetic serine protease inhibitor and an NF-κB inhibitor, in addition to paclitaxel were effective for suppressing peritoneal metastasis and increased survival time of mice with gastric cancer." (PMID 28350359, 2017). "The basic expression and functional role of NFKB1 and RELA (components of canonical NF-κB pathway) in gastric cancer (GC) have not been well elucidated." (PMID 26801246, 2016).